INS (insulin)
Diseases named in the same sentence as INS in open-access papers (continued):
Sharing a sentence is not in itself a finding about the gene and the disease.
Glucose intolerance (continued). "Here, we found that β cell–specific TRAPα-KO mice fed a chow diet or a high-fat diet (HFD) had decreased levels of circulating insulin, with age- and diet-related glucose intolerance." (PMID 40392602, 2025). "We previously reported that Gpr43 gene knockout mice exhibited a decreased β cell mass and developed glucose intolerance due to impaired insulin secretion under HFD feeding." (PMID 40944255, 2025). "Remarkably, CRT0066101 was highly effective in preventing insulin and glucose intolerance in HFD-fed mice." (PMID 41349796, 2025). "Estrogens promote insulin sensitivity, increasing insulin levels and activity, while progesterone reduces insulin efficacy and glucose transport, potentially leading to glucose intolerance." (PMID 40362828, 2025). "Reactive oxygen species (ROS), which are produced during metabolic dysfunction, can disrupt insulin signaling, damage cellular components, and promote inflammation, ultimately leading to adipocyte dysfunction and glucose intolerance." (PMID 40807540, 2025). "This was accompanied by protection against glucose intolerance, and increased insulin sensitivity, in females." (PMID 41219904, 2025). "Subsequent serum biochemical assays indicated that HFD feeding led to abnormal fasting blood glucose levels, glucose intolerance, decreased insulin sensitivity, and elevated insulin levels compared to chow-fed controls." (PMID 41492457, 2025). "Defects in insulin signaling appear, which further produce abnormal lipid profile, glucose intolerance, and steatosis of liver." (PMID 40356976, 2025). "In vivo, APs lowers blood glucose and insulin, improves glucose intolerance and IR, regulates lipids, and reduces OS." (PMID 41044789, 2025). "Consistent with our previous observations, mFicDR371S/R371S mice displayed glucose intolerance but remained responsive to insulin." (PMID 40073934, 2025). "Aligning with previous studies, C26 mice with mild cachexia housed at ST displayed glucose intolerance compared to controls, along with a trend towards elevated fasting blood glucose and insulin (+17% and +77%, respectively)." (PMID 40237521, 2025). "Research has also shown that enhancing insulin action within these brain regions can regulate peripheral metabolism, while inhibition of insulin receptors in specific regions of the hypothalamus led to impaired insulin secretion and glucose intolerance." (PMID 39439134, 2025). "Taken together, our data show that GPRC5B helps to maintain a mature β cell phenotype by regulating the cAMP/CREB/MafA pathway and that genetic inactivation of this receptor leads to reduced insulin secretion and glucose intolerance in HFD-fed mice." (PMID 40906536, 2025). "The rats on a high-carbohydrate, high-fat diet exhibited elevated insulin, glucose, and glucose intolerance, with deteriorated trabecular bone microarchitecture and smaller bones despite unchanged cortical thickness (Ct.Th)." (PMID 40564223, 2025). "Accordingly, a recent study showed reduced pancreatic size and mass of beta-cells, fewer mature insulin granules, and reduced insulin secretion and glucose intolerance in mice treated with atorvastatin." (PMID 39775321, 2025). "Body weight increased in a time-dependent manner and fasting blood glucose and insulin levels were significantly higher than those in chow-fed mice, indicating glucose intolerance." (PMID 41433229, 2025). "Suppression of Rspo3 exacerbated glucose intolerance and decreased insulin sensitivity in normal chow-fed iLiRspo3KO mice, with these non-beneficial effects persisting 2 months after tamoxifen administration." (PMID 39854351, 2025). "Separately, studies on the protein tyrosine phosphatase receptor N2 (PTPRN2, also known as phogrin or IA-2β) knockout murine models demonstrated mild glucose intolerance and modest reductions in pancreatic insulin content." (PMID 41010281, 2025). "Disruption of hepatic insulin signaling leads to glucose intolerance, increased gluconeogenesis, and hepatic steatosis." (PMID 38599845, 2024).
Glucose intolerance (continued). "A high dose of PA exposure suppresses the insulin signaling pathway in various cells and tissues, resulting in glucose intolerance and impaired insulin sensitivity." (PMID 39138413, 2024). "In terms of the metabolism, we found that maternal ALEs-rich diet increased body weight, blood glucose, and insulin levels of the offspring, and the offspring exhibited glucose intolerance." (PMID 38962449, 2024). "Insulin tolerance remained similar in WT and KO mice, but glucose intolerance with HFD was exacerbated in KO mice." (PMID 38829241, 2024). "HFD impaired glucose tolerance and insulin sensitivity in control mice, but HFD-fed TβRIIocy–/– mice showed glucose intolerance while maintaining insulin sensitivity." (PMID 39171528, 2024). "Mice lacking the β5i subunit of the immunoproteasome and fed with HFD for 2 months accumulate less fat and improve glucose intolerance and insulin sensitivity than wild-type mice fed with the same diet." (PMID 39095788, 2024). "To assess glucose intolerance and insulin sensitivity, we measured blood glucose and insulin levels." (PMID 39436946, 2024). "This study showed that Aβ infusion to the hippocampus attenuated insulin signaling in the hippocampus, increased neuroinflammation, and exacerbated systemic glucose intolerance and insulin resistance, resulting in an AD-like pathology in the animal model." (PMID 39337316, 2024). "Constitutive pleiotrophin deficiency contributes to morphological changes in pancreatic islets, accelerating age-related events such as glucose intolerance and decreased insulin sensitivity." (PMID 39456743, 2024). "Sodium glucose transporter 2 (SGLT2) inhibitors added to insulin therapy in type 2 diabetes (T2DM), have shown renoprotective and therapeutic effects on decreasing glycated hemoglobin (HbA1C), required insulin dosage, glucose intolerance, and body‐weight." (PMID 38923174, 2024). "Systemic chemical inhibition of CXCR3 led to significant metabolic changes, including increased body mass, reduced energy expenditure, elevated blood leptin, glucose intolerance, and decreased insulin levels." (PMID 39535032, 2024). "β cell-specific GRP94 KO resulted in aggravated glucose intolerance, reduced insulin secretion, and reduced β cell mass, whereas insulin sensitivity was unaffected." (PMID 38811543, 2024). "Comprehensive metabolic assessment of the immune system is needed to better understand the implications immune cell metabolic alterations in the progression from a healthy insulin-sensitive state toward glucose intolerance in children." (PMID 38680993, 2024). "Caffeic acid demonstrates hypoglycemic effects, enhances insulin levels, and ameliorates glucose intolerance." (PMID 38611548, 2024). "Further, Sirt5-knockdown mice showed marked abnormalities in glucose and lipid metabolism, manifested by increased serum triglyceride and leptin levels, glucose intolerance, and decreased insulin sensitivity and adiponectin levels." (PMID 39408844, 2024). "Our data also demonstrated that glucose intolerance, continuously elevated plasma insulin levels, reduced insulin response, and high liver glycogen levels were exclusively observed in male CJL mice." (PMID 39639385, 2024). "HNF1B is targeted by miR-802-dependent silencing, and it has been revealed that a short hairpin RNA (shRNA)-mediated reduction in HNF1B in the liver leads to glucose intolerance, damage to insulin signaling, and increased hepatic gluconeogenesis." (PMID 39337310, 2024). "One study showed that walnut green husk polysaccharide extracts inhibited insulin and glucose levels preventing chronic high-fructose diet-induced abnormal weight gain and glucose intolerance in mice, but A. muciniphila abundance was reduced." (PMID 39796314, 2024). "In these animals' glucose intolerance, increased blood glucose concentration, and insulin signaling disorder, along with upregulation of gluconeogenic genes in liver tissue were observed." (PMID 38975085, 2024).
Glucose intolerance (continued). "Insulin sensitivity declined with glucose intolerance (p value for trend <0.001) and was significantly lower in the IGT and CFRD groups compared with the NGT group." (PMID 39093413, 2024). "Loss of beta cell primary cilia postnatally results in the progressive disappearance of glucose-stimulated insulin secretion with accompanying glucose intolerance and a type 2 diabetes-like phenotype." (PMID 38353726, 2024). "We expressed GFP, Arg2, Arg2H160F, or Arg2Δ1-22 on an Arg2LKO background, and performed insulin and glucose intolerance testing after 4 to 5 weeks." (PMID 38280549, 2024). "We investigated a possible causal role for the elevated plasma LPA observed in male RT-SAKO mice in mediating reduced GLP-1 and insulin levels, and glucose intolerance, using Ki-16425, an LPAR1/3 antagonist." (PMID 38280449, 2024). "Npr1+/− mice developed a moderate glucose intolerance despite unchanged insulin sensitivity under SD." (PMID 39383215, 2024). "The pathophysiology of GDM is partially known, with alterations in the hormonal and metabolic profile during pregnancy leading to a decrease in insulin sensitivity, which can sometimes result in the development of glucose intolerance and GDM." (PMID 38999442, 2024). "Taken together, these findings strongly suggest that selective activation of Gs signaling in K cells stimulates the secretion of GIP and insulin when blood glucose levels are elevated, thus reversing the glucose intolerance characteristic of obese mice." (PMID 39436694, 2024). "Specifically, a loss of hepatic Glut2 has been demonstrated not only to lead to reduced glucose uptake but also long-term glucose intolerance due to suppressed glucose-stimulated insulin secretion (GSIS)." (PMID 37855335, 2024). "Our results show that Sox9-depleted rodent beta cells have defective insulin secretion, and aging animals develop glucose intolerance, mimicking the progressive degeneration observed in T2D." (PMID 38238288, 2024). "An intraperitoneal glucose tolerance test revealed glucose intolerance, with a blunted insulin secretion response." (PMID 38876803, 2024). "Mice lacking a functional pancreatic clock had impaired insulin release and glucose intolerance, indicating circadian control of insulin is crucial for maintaining glucose homeostasis during feeding and fasting periods." (PMID 39335475, 2024). "In our previous studies, we demonstrated that LP-programmed T2D rats had impaired insulin signaling, resulting in glucose intolerance and mitochondrial dysfunction in the GS muscles of female offspring." (PMID 39684571, 2024). "SREBP1c knockout mice exhibited glucose intolerance and low insulin levels, and their β-cells had a reduced ability to proliferate and secrete insulin." (PMID 39130628, 2024). "Overall, these findings indicate that both KD1 and KD2 induced glucose intolerance, likely attributable to insulin synthesis." (PMID 39398341, 2024). "Male mice fed a KD are particularly vulnerable to the development of glucose intolerance, particularly older mice that also experience a decrease in serum insulin." (PMID 39203867, 2024). "Despite glucose intolerance, insulin tolerance and fasted serum insulin levels were similar across groups." (PMID 38260478, 2024). "Muscular atrophy reduces the cellular targets for insulin activity, inducing glucose intolerance and stimulating gluconeogenesis, which then accelerates muscle wasting and protein catabolism, decreasing SCr levels in the process." (PMID 38919220, 2024). "Tipe1 deletion in db/db mice led to higher random and fasting blood glucose levels, lower fasting insulin levels, and severe glucose intolerance compared to Ins2‐Cre‐db/db mice." (PMID 38417114, 2024). "As the body’s intracellular responses to insulin progressively decline with age, this often results in glucose intolerance." (PMID 39367355, 2024).
Glucose intolerance (continued). "It has also been demonstrated that maternal ethanol exposure led to more severe glucose intolerance and insulin insensitivity in male offspring rats." (PMID 38263047, 2024). "The study also indicated that peripheral insulin sensitivity and disposition index diminished with worsening glucose intolerance, while the hepatic insulin sensitivity seemed unrelated to glucose tolerance status." (PMID 39093413, 2024). "Several of these studies indicated that insulin sensitivity decreases with glucose intolerance, as IGT and CFRD were associated with lower peripheral insulin sensitivity compared with normal glucose tolerance (NGT) in euglycaemic clamp studies." (PMID 39093413, 2024). "Liver-specific deletion of Agpat5 improved plasma insulin levels and glucose intolerance only in mice fed a chow diet supplemented with liquid sucrose." (PMID 39608054, 2024). "Fetub is considered to be a novel secretory adipokine/hepatic factor that is regulated in human steatosis (significantly increased in hepatic steatosis) and mediates impaired insulin action and glucose intolerance." (PMID 38783935, 2024). "In Wistar rats, feeding quinoa for 15 weeks improved glucose intolerance, pancreatic β-cell dysfunction, insulin resistance, and lipid accumulation." (PMID 39061898, 2024). "Some but not all previous metabolic clamp studies in CF have also reported a decline in insulin sensitivity in those with glucose intolerance." (PMID 39093413, 2024). "Decreased Nrf2 levels increase blood glucose levels, worsen glucose intolerance and impair insulin signaling." (PMID 39334959, 2024). "In mice, macrophage-specific knockdown of the inflammatory pathway significantly increased insulin sensitivity and protected them from glucose intolerance induced by high-fat diet." (PMID 39627688, 2024). "Long-term HFD feeding led to a detrimental impact on β cell function and insulin sensitivity and further contributed to glucose intolerance and T2D." (PMID 38811543, 2024). "Bempedoic acid was also shown to reduce fasting glucose, fasting insulin and glucose intolerance in mouse models, suggesting improvements in insulin sensitivity." (PMID 39202419, 2024). "Under a NCD, C57BL6/6J males display glucose intolerance compared to age-matched female controls, in part due to impaired insulin tolerance." (PMID 38393018, 2024). "This indicated that alternate mechanisms, besides systemic insulin resistance or changes in hepatic or peripheral glucose handling, should be explored to explain the observed glucose intolerance in male mice." (PMID 38280449, 2024). "Experiments on animals have indicated that glyphosate dose-dependently increased fasting plasma glucose (FPG) and serum insulin concentrations, compromised insulin function, and induced glucose intolerance via NFκB-mediated hepatic inflammation in rats." (PMID 39195702, 2024). "Molecularly, glucose intolerance can be explained in part by impaired insulin signaling in both the skeletal muscle and hepatic tissues." (PMID 38393018, 2024). "This manipulation impairs glucose homeostasis in mice fed on a standard diet: it promotes intraabdominal fat deposition, glucose intolerance, hyperinsulinemia and impaired insulin sensitivity, particularly in the context of moderate overweight." (PMID 39047908, 2024). "Consistently, the expression of anti-oxidant genes is decreased in the islets of β-cell-specific Hif2a knockout mice and these mice develop impaired insulin secretion and glucose intolerance when fed a high-fat diet." (PMID 38673770, 2024). "Ablation of YTHDC1 in β-cells of adult mice exhibits a significant decrease in insulin synthesis and secretion, as well as glucose intolerance." (PMID 39296713, 2024). "Our results showed long term intake of a HCA diet improved glucose homeostasis by improving insulin sensitivity, lowering glucose intolerance, and reducing glucose levels." (PMID 39300527, 2024).
Glucose intolerance (continued). "Liver-specific deletion of Agpat5 did not affect body weight or fat mass and yet still had improved plasma insulin levels and glucose intolerance when fed a chow diet supplemented with liquid sucrose." (PMID 39608054, 2024). "The NOD group showed glucose intolerance and increased insulin requirements, but normal insulin sensitivity." (PMID 39474247, 2024). "We found that G-1 improved glucose intolerance, which was supported by the observation that G-1 treatment stimulated insulin secretion from islets in a GPER-dependent manner." (PMID 39273478, 2024). "Genetic deletion of HDAC3 in mouse models has been shown to improve glucose intolerance and insulin sensitivity in the liver, skeletal muscle, and adipose tissue." (PMID 37674539, 2023). "Consistently, ATF6 overexpression in obese or diabetic livers regulates blood glucose level, reduces glucose intolerance and ameliorates insulin sensitivity." (PMID 37020593, 2023). "They demonstrated impaired insulin secretion and glucose intolerance in patients with PCC using the meal test and the homeostasis model assessment of β-cell function (HOMA-β)." (PMID 36982228, 2023). "In diabetic rats, it was demonstrated that ursolic acid (0.05% w/w) altered blood glucose levels and enhanced insulin sensitivity and glucose intolerance." (PMID 37408757, 2023). "Taken these together, the disordered glucose and insulin contributed to the IR of adipocytes and adipose tissue, while FC facilitated glucose intolerance and reinforced insulin sensitivity." (PMID 37710214, 2023). "Collectively, DAG inhibits the direct effect of insulin on supressing hepatic glucose production and peripheral tissue glucose disposal, which combined contributes to whole-body glucose intolerance." (PMID 37153211, 2023). "It is clear from the results presented here that Nnt deletion is not the only factor responsible for metabolic alterations as substrains with intact Nnt also showed glucose intolerance or high insulin levels." (PMID 37531359, 2023). "In rodents, FXR engagement was shown to inhibit NAFLD-related liver pathologies, as well as protect from insulin and glucose intolerance." (PMID 36994095, 2023). "Another study, conducted using the hyperglycemic clamp method in individuals with glucose intolerance, showed a positive correlation between 25(OH)D levels and insulin sensitivity." (PMID 36820117, 2023). "TRPC3 pharmacologic inhibition and knockout in mice lead to defective insulin secretion and glucose intolerance." (PMID 36642838, 2023). "Talin-1 deficiency impairs β-cell proliferation at least in part by decreasing Stat3 protein, resulting in reduced β-cell mass and insulin secretion, and glucose intolerance in mice." (PMID 37903776, 2023). "Taken together, these findings show that SERCA2 deletion in beta cells results in glucose intolerance and impaired insulin secretion." (PMID 37537395, 2023). "Mice were infused continuously with sEVs derived from the plasma of GDM patients and it was shown that GDM sEVs induced glucose intolerance, and reduced insulin sensitivity in vivo compared with mice infused with sEVs from NGT patients." (PMID 37650554, 2023). "DUSP4 overexpression did not affect glucose tolerance in control mice but significantly improved glucose intolerance and reduced plasma insulin levels in Dex-treated mice." (PMID 37253782, 2023). "Consistently, the pancreatic β cell-specific knockout of Mfn1/2 in mice (βMfn1/2 KO) led to several metabolic abnormalities, such as glucose intolerance, impaired glucose clearance, and a decrease in plasma insulin levels." (PMID 37762083, 2023). "The role of NLRP3 signaling was also confirmed in vivo as deletion of NLRP3 or anti-IL-1β treatment reversed the pro-inflammatory milieu in the gut, insulin secretion defect and glucose intolerance." (PMID 37400850, 2023).